CD40 (CD40 molecule)
Diseases named in the same sentence as CD40 in open-access papers (continued):
Sharing a sentence is not in itself a finding about the gene and the disease.
bladder cancer (23 papers, 2003 to 2025). "This Fc-enhanced anti-CD40 agonist antibody (2141-V11) was used for treatment in orthotopic murine bladder cancer models and achieved greater anti-tumor capabilities than both controls and BCG therapy through enhanced CD8+ T cell-dependent response." (PMID 40699676, 2025). "The human bladder TME shows enhanced CD40 expression, making it an ideal target to agonize for bladder cancer treatment." (PMID 40699676, 2025). "In bladder cancer tissue, the expression rate of CD40 in CD45+CD14+CD163- mono-macrophage subset was significantly lower than that in CD45+CD14+CD163+ mono-macrophage subset." (PMID 34803459, 2021). "Further, expression of CD-40 antigen on surface of bladder tumor cells also trigger the influx of TIL and immune cells in NMIBC resulting in increase in apoptosis of tumor cells, This indicate that development of anti-CD40 based test to target bladder cancer." (PMID 34094648, 2021). "To evaluate the value of CD40 as a biomarker in cisplatin-resistant bladder cancer, we established NPM1 silencing stable cell lines by lentivirus infection in three cisplatin-resistant bladder cancer cell lines." (PMID 32411234, 2020). "In this study, we first sought to investigate the gene expression profile following CD40 activation by either mCD40L delivered by replication-deficient recombinant adenoviral vector (RAdnCD40L) or sCD40L in the CD40-expressing bladder carcinoma T24 cells." (PMID 31941968, 2020). "To fully appreciate the differential effects of mCD40L and sCD40L on the outcome of CD40 ligation, we examined the transcriptional profiling of the bladder carcinoma T24 cells in response to CD40 ligation by either mCD40L or sCD40L." (PMID 31941968, 2020). "If we can determine the relationship between CD40 and functional proteins in drug-resistant bladder cancer, we can greatly expand the application of CD40." (PMID 32411234, 2020). "Western blot showed that the expression of CD40 in three NPM1 silencing bladder cancer cell lines was downregulated." (PMID 32411234, 2020). "Firstly, the CD40 status of bladder carcinoma cells, EJ, Hela cells and human alveolar basal epithelial carcinoma cells, A549, was determined." (PMID 20211016, 2010). "Our results also raise the possibility of the future development of CD40- and CD40 ligand-based immunotherapy for bladder cancer." (PMID 12592374, 2003). "CD40 is expressed not only on normal B lymphocytes and antigen-presenting cells but also on the surface of epithelioid tumors (cervical cancer, ovarian cancer, lung cancer, bladder cancer, and liver cancer) and hematological tumors." (PMID 39696986, 2024). "The expression of PLK1, GATA3, and CD40 were even related to the prognosis of bladder cancer." (PMID 36425941, 2022). "In addition, PPS was found to increase the expression level of CD86 and CD40 in bladder cancer tissue of rats, and regulate the immune activity of macrophages and promoted them to M1-like macrophages." (PMID 34034714, 2021). "It has been reported that CD40 signaling induces malignant cell death in many cancer types, including renal cell carcinoma, urothelial cell carcinoma, ovarian carcinoma, cervical carcinoma and bladder carcinoma." (PMID 34092233, 2021). "Because NPM1 can reflect the characteristics of bladder cancer, CD40 may be a more sensitive marker for monitoring the prognosis of bladder cancer." (PMID 32411234, 2020). "To control the specificity of CD40-mediated and caspase-8–dependent cell death in an in vitro assay with CD8+ T cells, human EJ138 bladder carcinoma cells, and A704 renal adenocarcinoma cells, we generated CD40−/− and caspase-8−/− variants of both lines." (PMID 40397730, 2025). "Recently, an anti-CD40 agonist called ADC-1013 was shown to induce a long-lasting antitumor response and T cell-dependent immunologic memory against bladder cancer." (PMID 36429020, 2022).
bladder cancer (continued). "The studies have shown that the CD40 molecule was found on the surface of antigen presenting cells (APC), normal bladder cancer, gastric cancer, colon cancer, and other solid tumors and hematological tumor cells." (PMID 32411234, 2020). "To verify and evaluate the value of CD40 as a noninvasive biomarker of cisplatin-resistant bladder cancer, we studied the expression of CD40 and the correlation between nucleophosmin (NPM1) and CD40 in cisplatin-resistant bladder cancer." (PMID 32411234, 2020). "Elsewhere, CD40 and HVEM messenger RNAs were coexpressed in the bioinformatic analysis of bladder cancer in the Cancer Genome Atlas database." (PMID 32722224, 2020). "There is a positive correlation between CD40 protein and NPM1 protein in drug-resistant bladder cancer." (PMID 32411234, 2020). "The expression of CD40 and NPM1 in three NPM1 silencing bladder cancer cell lines were detected by fluorescence microscopy and Western Blot." (PMID 32411234, 2020). "In addition, PPS had an inhibitory effect on the progression of bladder cancer in BBN-rat models and increased the effect on the expression levels of CD86 and CD40 in peritoneal macrophages." (PMID 34034714, 2021). "We believe that analysis of molecular markers such as BAX, BCL2, CD40 and CD40L may prove valuable in identifying patients with poor prognosis bladder cancers who may benefit from aggressive treatment and this should be considered in future trial design." (PMID 12592374, 2003). "However, up to now, the differential expression and predictive value of CD40 have not been verified in drug-resistant bladder cancer." (PMID 32411234, 2020). "However, the value of CD40 in drug-resistant bladder cancer has not yet been evaluated." (PMID 32411234, 2020). "Importantly, the induction of CD40 on cancer cells, but not normal cells, promotes apoptotic and/or necrotic signaling, which results in the cell death of renal cell carcinoma, urothelial cell carcinoma, ovarian carcinoma, cervical carcinoma and bladder carcinoma." (PMID 34092233, 2021).
Graves disease (23 papers, 2010 to 2025). Graves' disease is an autoimmune disorder that leads to overactivity of the thyroid gland (hyperthyroidism).It is caused by an abnormal immune system response that causes the thyroid gland to produce too much thyroid hormones. "Among these, PTPN22, CTLA4, HLA_DRB1, FCRL3, and IL2RA are common susceptibility genes between both conditions, while CD40 is exclusively associated with Graves’ disease and RA." (PMID 38093966, 2023). "Variants in the CD40 gene have been associated with several autoimmune diseases, including Graves’ hyperthyroidism, where they appear to influence thyroid antibody production and provide a predictive marker of relapse." (PMID 32845332, 2020). "Single-nucleotide polymorphism (SNP) haplotype and SNP-SNP interactions of CTLA-4 and CD40 genes, with susceptibility to Graves’ disease (GD), were explored in a Chinese Han population." (PMID 30223781, 2018). "In RA and Graves’ disease CD40 rs1883832 is associated with reduced CD40 expression and disease protection." (PMID 29312317, 2017). "Candidate gene studies reported the association of a functional CD40 polymorphism with Graves' disease; moreover, the association of this variant was replicated in populations of different ethnicity including Caucasians, Koreans, and Japanese." (PMID 20634952, 2010). "Mutations in CD40 have been widely reported to be risk factors for Graves’ disease (GD)." (PMID 34867801, 2021). "Functional studies have demonstrated that the disease-associated variant in CD40 alters the consensus Kozak initiation sequence, resulting in increased translational efficiency and suggesting that overexpression of CD40 has a causative association with the predisposition to Graves’ hyperthyroidism." (PMID 32845332, 2020). "The results showed that the pathway enrichment profile of WT mice after iodide matched significantly with that of a murine model of Graves’ disease (thyroid autoimmune disease associated with hyperthyroidism) (overall average z-score match = 39.69%) that overexpresses CD40 in the thyroid." (PMID 32961913, 2020). "This meta-analysis aims to evaluate whether the CD40 rs1883832 polymorphism is associated with Graves' disease (GD) risk in different populations." (PMID 30956635, 2019). "In addition, a single nucleotide polymorphism (SNP) C/T in the untranslated region of the CD40 gene has been associated with susceptibility to Graves' disease in Caucasian and Korean populations." (PMID 25653477, 2015). "In addition, CD40 polymorphisms have roles in predicting infection- and autoimmunity-associated diseases, such as Grave's disease and coronary artery calcification." (PMID 21912605, 2011). "PTPN22, IL-2RA/CD25, CD40, and SCGB3A2 genes were shown to be associated with Graves’ disease (GD) using candidate gene studies." (PMID 31066758, 2019). "In Grave’s disease, up-regulation of CD40 by rs1883832 places an individual at an increased disease risk." (PMID 24828072, 2014). "Considering that rs1883832 genotypes influence the translation of CD40, we propose that through transcriptional and translational pathophysiological aspects, rs1883832 alters CD40 gene expression, which ultimately contributes to Graves’ disease etiology." (PMID 34867801, 2021). "Indeed, several different murine models have confirmed that either genetic or chemical modulation of CD40 signaling can modify the severity of autoimmune thyroiditis or thyroid autoantibody production, establishing CD40 as a potential therapeutic target in the treatment of Graves’ hyperthyroidism." (PMID 32845332, 2020). "A recent study has showed that CD40 activation up-regulates expression of the p65 and p52 subunits of NF-κB in human primary thyroid cell cultures from Graves' patients, which indicates an involvement of both the canonical and noncanonical NF-κB pathways in CD40 signaling in Graves' disease." (PMID 30186235, 2018).
Stroke (23 papers, 2012 to 2025). Sudden impairment of blood flow to a part of the brain due to occlusion or rupture of an artery to the brain. "This is consistent with the findings of several Mendelian randomization studies, which have shown that CD40 is associated with a reduce risk of aortic disease, enhanced cognitive function, and a decreased risk of stroke." (PMID 38887301, 2024). "Conversely, a decreased susceptibility to stroke was associated with increased CD40 expression on monocytes, particularly on CD14+ CD16+ and CD14+ CD16- monocytes, with the latter two showing the most compelling evidence." (PMID 38887301, 2024). "Our research indicates that the decreased susceptibility to stroke is associated with an increase in the expression of CD40 in monocytes, particularly in CD14+ CD16+ and CD14+ CD16- monocytes, with the latter two demonstrating the most compelling evidence." (PMID 38887301, 2024). "Our study revealed a positive correlation between CD40 and stroke risk, providing compelling evidence for CD40 as a potential biomarker." (PMID 39253091, 2024). "CD40 has previously been associated with stroke risk, infarct size and worse clinical outcomes post-stroke." (PMID 37685924, 2023). "Transcriptional analysis confirmed a reduction in expression of co-stimulatory genes in the spleen known to be expressed by macrophages 1–5 days after experimental stroke including Cd40, Cd80, Cd86, Icam1, Tnfsf9, which encodes 4-1BBL, and Cd274." (PMID 29872438, 2018). "CD40+ B-cells have also been associated with a higher risk of stroke in the future." (PMID 39899926, 2025). "However, these observational associations are insufficient to establish a causal relationship between CD40 and stroke." (PMID 38887301, 2024). "CD19 + CD40+ B cells are associated with a low risk of stroke." (PMID 38221996, 2023). "In a large human follow-up study, different roles have been identified for the expression of CD86 and CD40 on peripheral B cells; whereas high levels of CD19+CD40+ B cells were associated with a decreased risk of stroke, the opposite association was found for CD19+CD86+ cells." (PMID 33572939, 2021). "Two markers associated with post-stroke epilepsy are mutations in CD-40-1C/T or Rs671 genes." (PMID 34827090, 2021). "In a case–case prospective study, CD40-1C>T polymorphism (rs1883832) in peripheral blood was found to be associated with brain vessel re-occlusion after fibrinolysis in the early phase (within 3 h) after stroke onset." (PMID 34168606, 2021). "In short, CD40-1C>T polymorphism (rs1883832) can predict brain vessel re-occlusion after fibrinolysis after stroke onset; and genes may be potential biomarkers in assessing the complications of hyperacute IS." (PMID 34168606, 2021). "In our study, elevated CD40 expression may be associated with decreased susceptibility to stroke." (PMID 38887301, 2024). "However, it has been hypothesized that T-cell and CD40-dependent B-cell responses are proatherogenic circulating CD40+ B cells correlated with a reduced risk of stroke, which may be related to the importance of CD40 in Breg differentiation." (PMID 34445084, 2021). "The genetic associations with stroke colocalize (Posterior Probability >0.7) with the genetic associations of four proteins (TFPI, TMPRSS5, CD6, CD40)." (PMID 36253349, 2022). "In patients with epilepsy following a stroke, plasma sCD40L levels and CD40 expression in leukocytes were significantly elevated." (PMID 35456932, 2022). "The influx of DCs into the brain increases dramatically post-stroke and is associated with elevated expression of co-stimulatory molecules MHCII, CD40, and CD80." (PMID 31736685, 2019). "Microglial CD40 expression was high 24 and 48 hr post‐stroke in both groups and by 1 week dramatically dropped off (p < .05 vs. 24 hr)." (PMID 28523230, 2017). "In the transient MCAO stroke model in mice, a monoclonal antibody against CD40 was conjugated to Cy5.5 and used to evaluate CD40 expression in the brain." (PMID 25525560, 2014).
Stroke (continued). "CD40 is a costimulatory protein on antigen-presenting cells that is essential for immune responses, and its role in inflammatory pathways suggests a potential link to ischemic stroke, as inflammation is a critical component in stroke pathophysiology." (PMID 40624693, 2025). "In addition, the OR (95%CI) of stroke per SD increase in genetically predicted immune cells was 0.970 (0.952, 0.989) for CD40 on CD14+ CD16+ monocyte, 0.976 (0.962, 0.990) for CD40 on monocyte and 0.969 (0.948, 0.990) for CD40 on CD14+ CD16- monocyte." (PMID 38887301, 2024). "The association of the genetic variants selected as instrumental variables for four proteins (TFPI, TMPRSS5, CD40 and CD6) colocalized with the stroke associations (posterior probability (PP) ≥0.7) i.e. the associations in these regions were likely due to the same underlying causal variants." (PMID 36253349, 2022). "TFPI, CD40, IL6RA and MMP12 were associated with a lower risk of any stroke and any ischaemic stroke, while TMPRSS5 and CD6 was associated with a higher risk of any stroke." (PMID 36253349, 2022). "However, we report that CD40+ microglia and macrophages are highest 24–48 hr after stroke and decrease by 1 week post‐stroke." (PMID 28523230, 2017). "Upregulation of CD40 and/or CD40Lhave been detected in serum/plasma/cell surface of patients with IS by several studies,and were suggested to be useful predictors and biomarker for stroke." (PMID 28590502, 2017). "Notably, we found for TFPI, CD40 and CD6 that >80% of the posterior probability of colocalization of the primary genetic association with stroke and the respective protein levels were explained by a single variant (rs67492154, rs4810485 and rs2074227 for TFPI, CD40 and CD6, respectively)." (PMID 36253349, 2022). "Similarly, CD6 pQTLs colocalized with any stroke genetic associations; CD40 pQTLs colocalized with the genetic associations for any stroke, any ischaemic stroke and large artery stroke; TMPRSS5 pQTLs colocalized with any stroke, any ischaemic stroke and cardioembolic stroke genetic associations." (PMID 36253349, 2022). "We, therefore, focused further analyses on the proteins with cis-pQTLs only (i.e. TFPI, TMPRSS5, CD40, MMP12, IL6RA, CD6), as these associations with stroke are unlikely to be due to pleiotropy." (PMID 36253349, 2022).